RNU4-59P (RNA, U4 small nuclear 59, pseudogene)
Gene: Small nuclear RNA gene on chromosome 1 (92,700,819 to 92,700,934, reverse strand). Ensembl gene ENSG00000201317.
Homologues: Orthologues: chimpanzee U4 (99% identical), macaque U4 (78% identical), dog U4 (66% identical), rat LOC120093499 (65% identical), rat U4 (64% identical), dog U4 (59% identical), rabbit U4 (58% identical), dog U4 (55% identical), guinea pig U4 (55% identical). Paralogues in human: RNU4-72P (70% identical), RNU4-91P (70% identical), RNU4-53P (69% identical), RNU4-4P (68% identical), U4 (67% identical), RNU4-24P (66% identical), RNU4-36P (66% identical), RNU4-15P (65% identical), RNU4-77P (65% identical), RNU4-81P (65% identical), RNU4-90P (65% identical), RNU4-10P (64% identical), and 80 more.